IL1B (interleukin 1 beta)
Diseases named in the same sentence as IL1B in open-access papers (continued):
Sharing a sentence is not in itself a finding about the gene and the disease.
microcephaly (9 papers, 2019 to 2024). A congenital or acquired developmental disorder in which the circumference of the head is smaller than normal for the person's age and sex. "Moreover, apoptosis-induced microcephaly alterations have been linked to high proinflammatory cytokines production, for instance TNFα and IL-1β." (PMID 33251156, 2020). "A cerebral organoid is useful to study immune responses, particularly in Zika-induced microcephaly IL-8, IL-1β, TNF-α, and IFN-γ reportedly induce intestinal inflammation caused by Entamoeba histolytica." (PMID 38900784, 2024). "When the groups of neonates with microcephaly and controls were compared, we identified the top discriminant scores for IL-1β, IL-3, EOTAXIN (CCL11) and IL-12p70." (PMID 33875756, 2021). "We have shown that IL-1β is activated in HUVECs infected with both ZIKV strains, suggesting that the pathogenesis of ZIKV-caused microcephaly is complex, where crossing the placenta and targeting neuronal progenitors are essential." (PMID 31249527, 2019). "Unsupervised hierarchical cluster analysis demonstrated that ZIKV-exposed individuals with microcephaly exhibited a tendency of increased levels of pro-inflammatory mediators in CSF, as IL-1β, IL-12p70, IL-15, IL-17A, IFN-γ, and MIP-1α (CCL3) compared to controls." (PMID 33875756, 2021). "Associated with other mediators such as IL-3, IL-1β; eotaxin was considered as a differential marker in children exposed in utero to ZIKV, born with or without microcephaly." (PMID 36146688, 2022). "In the canonical coefficient analysis between controls and those exposed to ZIKV without microcephaly, we found that IL-1β, IL-3, IL-4, IL-7 and EOTAXIN (CCL11) were the top CSF markers in our model." (PMID 33875756, 2021). "Presence of NLRP1, NLRP3, and AIM2 together with elevated IL-1β, IL-18, and IL-33 could be detected in the brain of ZIKV-infected patients with microcephaly." (PMID 33796483, 2021). "Our data demonstrating ZIKV-induced IL-1β secretion from hNPCs, as well as previous findings on ZIKV-induced inflammasome, highlight the potential role of ZIKV-mediated inflammasome activation in neurodevelopmental defects, including microcephaly." (PMID 33207682, 2020).
Mycobacterium infection (9 papers, 2013 to 2025). Infections with bacteria of the genus Mycobacterium. "High IL-1β production and high mortality were unexpectedly found in M. tb-infected mice deficient in caspase-1 implicates the existence of caspase-1 independent IL-1β production in mycobacterial infection." (PMID 29228045, 2017). "We still cannot exclude the possibility that il1β, another significantly increased mycobacterial infection-related cytokine, also plays a role in SAL-mediated protection, which is worth further exploration in the future." (PMID 36120339, 2022). "Zebrafish macrophages show stabilization of Hif1α and il-1β expression following mycobacterial infection." (PMID 32158446, 2020). "Mice defective in IL-1R or IL-1β are more sensitive to mycobacterial infection and have an increased bacterial burden." (PMID 30846986, 2019). "IL-1β is a critical innate cytokine in mycobacterial infection and has complex cross-talk with other mediators within the complex inflammatory network consisting of IL-1β, TNF-α, eicosanoids, chemokines, and Th17 response." (PMID 29228045, 2017). "Previous studies, including our own, have indicated that decreased ROS levels lead to a lower inflammasome activation and IL-1β production in mycobacterial infection in macrophages." (PMID 29228045, 2017). "The increase in susceptibility of IL-1R-deficient mice results from the recruitment of defective immune cells to the site of infection and a deficiency in the formation of proper granuloma; these changes indicate the vital significance of IL-1β signaling to fight against mycobacterial infection." (PMID 30846986, 2019). "However, recent studies have shown that neutrophils play an important role in IL-1β production during mycobacterial infection." (PMID 29228045, 2017). "Blocking of IL-1β may therefore ameliorate this neutrophilic inflammation in mycobacterial pulmonary infection." (PMID 29228045, 2017). "In this study, we showed that ROS-deficiency leads to an early and extensive neutrophilic inflammation, which may contribute to the elevated IL-1β production in mycobacterial infection." (PMID 29228045, 2017). "We therefore postulated that neutrophils may be involved in the linkage between ROS and IL-1β in mycobacterial infection." (PMID 29228045, 2017). "Along the same line of high IL-1β levels found in Ncf1-/- mice reported in this study, those results underscore the importance of the redox regulation of the acute inflammation cytokine IL-1β in mycobacterial infection in the lung." (PMID 29228045, 2017). "Indeed, we found that neutrophils, which are more abundant in the Ncf1-/- mice with mycobacterial infection, produced more IL-1β and the protease NE in neutrophils was capable of processing pro-IL-1β." (PMID 29228045, 2017). "However, the specific role of IL-1β in the host-detrimental tissue inflammation during mycobacterial infection remains unclear due to the difficulty in comparing the severity of granulomatous inflammation without equalizing mycobacterial loads in different mouse strains." (PMID 29228045, 2017). "miR-146a modulates the inflammatory response upon Mycobacterium infection in Raw 264.7 cells by targeting IRAK1 and TRAF6, resulting in remarkably reduced translation of IL-6, IL-1β, and TNF-α." (PMID 27803700, 2016). "miR-99b upregulation has been observed to stimulate the production of proinflammatory cytokines such as IL-6, IL-12, IL-1β, and TNF-α in macrophages and DCs upon Mycobacterium infection." (PMID 27803700, 2016). "An emerging body of evidence suggests that IL-1β plays a key role in the control of mycobacterium infection, it is reasonable to speculate that ERS boosts immunologic defense through IL-1β secretion after M. bovis infection." (PMID 30846986, 2019).
myelofibrosis (9 papers, 2015 to 2025). A partial or complete replacement of the bone marrow stroma by fibrous tissue. "Thus, transplantation of VF;IL-1β−/− bone marrow into IL-1β deficient recipients, similar to complete IL-1β knockout, abolished the beneficial effects on myelofibrosis and osteosclerosis." (PMID 36100613, 2022). "The efficacy of this approach has been proven in JAK2V617F-expressing mice, where inhibition of IL-1β with anti-IL-1β antibody alone or in combination with ruxolitinib had beneficial effects on myelofibrosis and osteosclerosis." (PMID 37284191, 2023). "Genetic deletion of IL-1β from JAK2-V617F mutant cells, or pharmacological inhibition of IL-1β are effective in reducing myelofibrosis and osteosclerosis in a preclinical mouse model of MPN." (PMID 36100613, 2022). "Using genetic and pharmacological approaches, we show that IL-1β inhibition reduced myelofibrosis in a preclinical JAK2-V617F MPN mouse model." (PMID 36100613, 2022). "The anti-IL-1β antibody showed additive effects with ruxolitinib in reducing myelofibrosis, osteosclerosis as well as inflammatory cytokines in MPN mice." (PMID 36100613, 2022). "As a consequence, nestin-positive MSCs were preserved in bone marrow of VF;IL-1β−/− mice and the presence of nestin-positive MSCs correlated with reduced myelofibrosis." (PMID 36100613, 2022). "Nevertheless, anti-IL-1β antibody alone effectively eliminated IL-1β protein, reduced platelet counts and also reduced the grade of myelofibrosis compared with vehicle." (PMID 36100613, 2022). "Inhibition of IL-1β in JAK2-V617F mutant mice by anti-IL-1β antibody also reduces myelofibrosis and osteosclerosis and shows additive effects with ruxolitinib." (PMID 36100613, 2022). "Our data highlight the role of IL-1β in MPN disease progression to myelofibrosis and provide a rationale for a clinical trial with anti-IL-1β antibody in MPN." (PMID 36100613, 2022). "Loss of IL-1β in JAK2-mutant hematopoietic cells prevented these alterations and correlates with reduced MPN progression to myelofibrosis and osteosclerosis." (PMID 36100613, 2022). "Since the genetic deletion of IL-1β in hematopoietic cell showed beneficial effects on myelofibrosis, we also tested the effects of pharmacological inhibition of IL-1β." (PMID 36100613, 2022). "The mechanism by which IL-1β promotes myelofibrosis involves direct effects on megakaryopoiesis and on bone marrow microenvironment." (PMID 36100613, 2022). "The beneficial effects on myelofibrosis and osteosclerosis in our mouse models strongly correlated with the reduction in platelet counts in the various settings of inhibiting or deleting IL-1β." (PMID 36100613, 2022). "Until week 20, platelet counts in recipients of VF;IL-1β−/− bone marrow were lower than in mice transplanted with VF bone marrow and at 16 weeks there was a trend towards lower grade of myelofibrosis." (PMID 36100613, 2022). "In particular, induction of JAK2V617F leads to a significant inflammatory response consistent with recent studies demonstrating the involvement of IL-1β in the development of myelofibrosis in a JAK2V617F mouse model." (PMID 32707883, 2020). "Consistently, JAK2V617F-positive hematopoietic stem cells secrete IL1β inducing inflammation and promoting bone marrow myelofibrosis also in animal models." (PMID 32707883, 2020). "Ruxolitinib alleviates constitutional symptoms of myelofibrosis (MF) by downregulating interleukin (IL)-1b, IL-6 and TNF-α." (PMID 30700842, 2019). "The observed inflammasome activation following JAK2V617F induction is consistent with a recent report demonstrating the involvement of IL1B in myelofibrosis development in a JAK2V617F model mouse." (PMID 26823993, 2015). "Through regulation of the miRNA rs2431697 genotype and NLRP3, NF-κB1, and IL-1β genes, new therapeutic strategies could be considered to prevent myelofibrosis progression in MPN patients." (PMID 36902299, 2023).
myelofibrosis (continued). "Thus, contrary to the expectations from the complete genetic ablation of IL-1β in all tissues, pharmacological inhibition of IL-1β showed beneficial effects on myelofibrosis and course of the disease in VF mice comparable to the genetic ablation of IL-1β in hematopoietic tissues only." (PMID 36100613, 2022). "Interestingly, we found that ruxolitinib, a specific JAK1/2 inhibitor which used for myelofibrosis treatment, could substantially reduce plasma IL-6, IL-1β, IFN-γ and TNF-α contents in atherosclerotic rabbits." (PMID 32169038, 2020). "Using D9 cells, we identified several genes involved in the inflammasome pathway, such as AIM2, IL1B, and CASP1, as downstream targets of JAK2V617F, which could explain the molecular mechanism behind myelofibrosis development in patients harboring the JAK2V617F mutation." (PMID 26823993, 2015). "Selinexor has also been shown to reduce the plasma levels of many key pro-inflammatory cytokines (e.g., IL-6, TGFβ, IL-1β, IL-10, IFN-γ, TNF-α) in patients with myelofibrosis, and also in ex vivo studies with PBMCs." (PMID 40565816, 2025). "More recently, IL1B secreted from JAK2V617F-positive hematopoietic stem cells has been shown to induce inflammation and promote the development of myelofibrosis in the bone marrow in animal models." (PMID 26823993, 2015). "Knockout of IL-1β in hematopoietic cells of JAK2-V617F mice reduces inflammatory cytokines, prevents damage to nestin-positive niche cells and reduces megakaryopoiesis, resulting in decrease of myelofibrosis and osteosclerosis." (PMID 36100613, 2022).
oral diseases (9 papers, 2018 to 2026). "Since both IL-1α and IL-1β are implicated in the pathology of OM, and IL-1α at least partially regulates neutrophils in other oral diseases, we asked if blocking IL-1R in WT and Il17ra−/− mice would account for the increased damage when IL-17RA is lacking." (PMID 34220843, 2021). "Both TNF-α and IL-1β are also considered to be possible indicators of malignant transformation in oral disorders." (PMID 34064411, 2021). "With biomarkers like IL-1β, IL-6 and TNF-α helpful in determining theinflammatory status in oral disorders, the dynamic nature of saliva permits immediate tracking of progressing illness and therapyresponses." (PMID 40230914, 2024).
ovarian tumor (9 papers, 2012 to 2025). "A novel mouse model that utilizes transgenic female mice bearing ovarian tumors to study cancer cachexia.Notable biomarkers of this model are, growth differentiating factor 15, interleukin-6, interleukin-1 beta, and tumor necrosis factor alpha." (PMID 37755304, 2023). "Immunohistochemical evaluation of ovarian tumor tissues revealed a significant correlation between with IL-1β expression and overall survival." (PMID 22296757, 2012). "In combination, these analyses show that the increased adhesion of MFOC3 to MCs is influenced by the release of IL-1β released from the ovarian tumor cells, and one consequence of this is the induction of cell surface β1 integrin on MCs." (PMID 22296757, 2012). "Thus, the IL-1β/integrin axis may not only advance initial cell adhesion of ovarian tumor cells to the peritoneum, but trigger a cascade of events that favor the establishment of dispersed secondary tumors." (PMID 22296757, 2012). "It is well-known that pro-inflammatory cytokines, particularly IL-1β, IL-6 or TNF-α, promote ovarian tumor growth and metastasis, and their high serum levels are correlated with poor clinical outcomes." (PMID 34771587, 2021). "Similar to the chicken, CASP1 (2.7x; p = 0.05), IL1β (4.9x; p = 0.04) and IL18 (33x; p = 0.02) mRNA were significantly higher in human ovarian tumors." (PMID 31923221, 2020). "The study objective was to determine if the NLRP3 inflammasome components (NLRP3, caspase-1), and the corresponding cytokine products, IL1β and IL18, were increased in ovarian tumors." (PMID 31923221, 2020). "The Human Protein Atlas suggests human ovarian tumors express NLRP3, caspase-1, IL1β and IL18." (PMID 31923221, 2020). "Therefore, we speculated here, that the increased levels of the pro-inflammatory cytokines, IL-1β, IL-6 and TNF-α in tumor-bearing mice is dependent on the production of TNF-α by ovarian tumor cells." (PMID 37305383, 2023).
Pain (9 papers, 2008 to 2025). An unpleasant sensory and emotional experience associated with actual or potential tissue damage, or described in terms of such damage. "The most relevant cytokines observed in PTX-induced neuropathic pain are IL-1β, IL-8, and TNF-α, as well as IL-6, IL-4, and IL-10." (PMID 40006070, 2025). "This study examined the effect of endurance training on the expression of NLRP3, P38 MAPK, TNF-α, and IL-1β genes in the spinal cord of rats with diabetic neuropathic pain." (PMID 35655729, 2022). "Previous studies have reported that microglial activation induces extensive production of proinflammatory cytokines, such as TNF-α, IL-6, and IL-1β, which are involved in the pathogenesis of neuropathic pain." (PMID 32171293, 2020). "Additionally, we examine whether inhibiting LFA-1 or IL-1β actions in the spinal cord (intrathecal; i.t., route) could alleviate chronic neuropathic pain and reduce spinal and DRG glial activation markers, proinflammatory cytokines, and elevate anti-inflammatory cytokines." (PMID 30961664, 2019). "Increased levels of TNF-α, IL-1β, and IL-6 have been observed both in the DRG and SDH in the spinal nerve ligation model of neuropathic pain." (PMID 23365595, 2012). "Besides, proinflammatory cytokines, including tumor necrosis factor-alpha (TNF-α) and interleukin-1 beta (IL-1β), also play a crucial role in VCR-induced neuropathic pain." (PMID 34199936, 2021). "It is known that serum levels of proinflammatory cytokines such as IL-1β, IL-6, and TNF-α are significantly upregulated during chronic neuropathic pain and anti-inflammatory cytokines such as IL-10 are significantly downregulated during chronic neuropathic pain state." (PMID 30755780, 2019).
pertussis (9 papers, 2016 to 2025). A contagious bacterial respiratory infection caused by Bordetella pertussis. "In bone marrow derived macrophages, aerobic glycolysis promotes IL-1β production upon LPS stimulation or Bordetella pertussis infection." (PMID 34737406, 2021). "Our current in vivo study demonstrated that immunization with an OMV-based pertussis vaccine (omvPV) in comparison to wPV elicited reduced concentrations of serum pro-inflammatory cytokines (IL-1α, IL-1β, and IL-6), chemokines (CXCL1 and CXCL10), and G-CSF." (PMID 27905535, 2016). "The role of IL-1β in protection against pertussis was suggested using the murine protection model." (PMID 32973778, 2020). "Using the Bordetella pertussis (etiologic agent of the respiratory disease named pertussis) in vitro infection model there is evidence of inflammasome activation in human and murine macrophages and, the protective IL-1β response was demonstrated to be caspase-1-independent." (PMID 32973778, 2020). "Despite this, we nonetheless demonstrate that heterologous IL-1β and IL-6 responses 3 months after BCG vaccination, i.e. at the moment of Tdap-IPV vaccination, but not 2 weeks after BCG vaccination are associated with enhanced pertussis humoral and cellular immunity." (PMID 35177621, 2022). "Furthermore, increases in pertussis antibodies, total IgG-switched MBC responses, and IFNγ in response to PT restimulation in the BCG-trained cohort were associated with innate responses, in particular IL-1β and IL-6." (PMID 35177621, 2022). "For the Pertussis pathway, the main responsible genes for the pathways were CASP3, IL-1β, IL-1, IL-6, TNFα, and iNOS." (PMID 37895148, 2023). "Unlike a parenterally delivered whole-cell pertussis vaccine, which induced high levels of serum IL-1β, IL-6, tumour necrosis factor and C-reactive protein, aerosol immunization with the AIBP vaccine did not promote systemic pro-inflammatory responses." (PMID 41214155, 2025).
retinal diseases (9 papers, 2013 to 2025). "The roles of angiogenic and proinflammatory factors, including VEGF, TNF, TGFB1, CASP3, IL6, IFNG, and IL1B, and their association with miRNAs and the specified proteins in retinal diseases have been previously reported." (PMID 36180575, 2022). "On the contrary, the expression of the gene for IL-1β, a cytokine involved in several retinal diseases, was significantly decreased during cultivation of CD45/CD11b positive cells with all tested concentrations of AgNPs." (PMID 39190103, 2025). "The IL-1β cytokine binds to the IL-1RI receptor and is an established biomarker for retinal diseases." (PMID 35576057, 2022). "Furthermore, cytokine inhibitors, such as TNF-α blockers (adalimumab, infliximab), IL-6 antagonists (tocilizumab), and IL-1β inhibitors (canakinumab), are being actively explored for their potential to reduce chronic inflammation in retinal diseases." (PMID 40722794, 2025). "IL-1β is a critical inflammatory cytokine involved in various retinal diseases." (PMID 32714489, 2020). "The importance of IL‐1β in retinal diseases makes IL‐1 inhibition a therapeutic option." (PMID 30224384, 2018). "Data on the efficacy of IL‐1β inhibition therapy in inflammasome‐related retinal diseases are currently lacking." (PMID 30224384, 2018). "Moreover, the present in vitro findings contrasted these two VEGFR2 ligands in terms of the preferential gene upregulation of LGALS1 by IL-1β and VEGF165 by hypoxia in Müller glial cells, which are activated in various retinal diseases." (PMID 29170525, 2017).